CST3 (cystatin C)
Diseases named in the same sentence as CST3 in open-access papers (continued):
Sharing a sentence is not in itself a finding about the gene and the disease.
Obesity (continued). "In conclusion we found stabilisation in renal function as measured by 51Cr-EDTA GFR or Cystatin C related assessments in patients with CKD 12 months after obesity surgery." (PMID 30594245, 2018). "We show that EV-cystatin C was positively related to metabolic complications of obesity, including low-grade systemic inflammation, low HDL-cholesterol levels and metabolic syndrome." (PMID 24498934, 2014). "Additionally, obesity, socioeconomic deprivation, elevated C-reactive protein, triglyceride, vitamin D, HbA1c, cystatin C, urate, and alanine aminotransferase, and decreased HDL cholesterol and IGF-1, as well as CKD and COPD, were associated with LC." (PMID 40738888, 2025). "Cystatin C is known to be independent from muscle mass, but potentially influenced by obesity." (PMID 39792299, 2025). "The 2-sample MR indicated a potential causal association between OSA and renal impairment, and the MVMR results demonstrated that obesity mediates the causal relationship between OSA and several measures of renal impairment, such as eGFRcystatin c, BUN, and serum cystatin C." (PMID 39928765, 2025). "On the contrary, obesity was still associated with eGFRcystatin c (OR = 0.990, 95% CI: 0.984–0.997, P < .05), BUN levels (OR = 1.065, 95% CI: 1.036–1.096, P < .05), and cystatin C levels (OR = 1.051, 95% CI: 1.016–1.088, P < .05), the same result was also shown in LASSO." (PMID 39928765, 2025). "Cystatin C is generated in all nucleated cells and is less affected by muscle mass than creatinine but has been shown to be affected by levels of thyroid hormones, corticosteroids and possibly by obesity, smoking and inflammation." (PMID 40383727, 2025). "While cystatin C‐based eGFR (eGFRCYS) is less affected by muscle mass, it may underestimate kidney function in patients with obesity." (PMID 38646842, 2024). "Furthermore, cystatin C concentrations can be influenced by obesity, inflammation, steroid intake, or thyroid function." (PMID 38313686, 2024). "Measured GFR is one of the most accurate tests to certify GFR levels; an alternative test to measure renal function is Cystatin C but this is influenced by other non-GFR-related factors such as obesity, thyroid function, and cardiovascular risk factors." (PMID 37444086, 2023). "The present study showed that the elevated circulating cystatin C levels in study participants with obesity may be to counteract obesity-related inflammation." (PMID 35185798, 2022). "The association between serum cystatin C levels and obesity has not been fully explored in adolescents." (PMID 35185798, 2022). "Girls with obesity had higher cystatin C levels compared with girls with normal BMI (P = 0.003)." (PMID 35185798, 2022). "It used the serum cystatin C level as an indicator of early obesity in adolescents to promote early preventive intervention for overweight or obesity so as to reduce the incidence of obesity and obesity-related diseases in adults." (PMID 35185798, 2022). "Cystatin C expression in human adipose tissue could in part explain increased serum cystatin C levels in obesity." (PMID 35862349, 2022). "Whether normal cystatin C values ranges for boys and girls separately need to be developed in the future for early diagnosis of obesity remains to be explored." (PMID 35185798, 2022). "The initial hypothesis could be that serum cystatin C and uric acid might aspire to be early markers of kidney damage in obesity, getting ahead of an increase in the concentration of creatinine, urea, and hypofiltration." (PMID 34442019, 2021). "Low dietary intake, fluid overload, and chronic liver disease lower serum creatinine levels; hyperthyroidism and corticosteroid use increase serum cystatin C levels; inflammation and obesity reduce serum creatinine while simultaneously elevating cystatin C levels." (PMID 34413438, 2021). "Cystatin C and uric acid might aspire to be early markers of kidney damage leading to obesity-related glomerulopathy." (PMID 34442019, 2021).
Obesity (continued). "Increased serum cystatin C and uric acid might aspire to be early markers of kidney damage leading to obesity-related glomerulopathy." (PMID 34442019, 2021). "Associations for obesity and morbid obesity, and higher levels of cystatin C did not survive adjustment for biological or medical factors." (PMID 33587202, 2021). "It has been suggested that cystatin C levels are modified by obesity and inflammation." (PMID 31799980, 2020). "Cystatin C-based eGFR is less influenced by age or ethnicity, but other factors such as obesity, inflammation, and smoking as well as intake of glucocorticoids may affect serum values." (PMID 33161898, 2020). "In particular, in stage 2 CKD, its growth is associated with an increase in cystatin C levels and a decrease in glomerular filtration rate and probably the progression of obesity, while in stage 1, such a relationship is not yet formed." (PMID 33456602, 2020). "Epidemiological studies have shown serum cystatin C to be increased in humans with obesity." (PMID 28922364, 2017). "In patients with clinically manifest vascular disease, EV-cystatin C positively relates to metabolic complications of obesity, and may thus contribute to an increased cardiovascular risk through obesity associated metabolic dysfunction." (PMID 24498934, 2014). "Although elevated cystatin C levels may be associated with obesity, recent research has shown that obesity does not affect the prognostic value of cystatin C for estimating the risk of adverse outcomes." (PMID 39774287, 2025). "Cystatin C is not affected by muscle mass, but the difficulty in the setting of obesity and weight loss is that it may be affected by fat mass." (PMID 38796653, 2024). "It is also important to note that the novel EC proteins, APP, CAD, BRD2 (which is part of DKFZp313H139), CST3, GRN, PPM1G and ZC3H4, have all been reported to be positively associated with obesity or adiposity, whilst the novel EC protein SLC25A24 may even prevent obesity and promote leanness." (PMID 37760635, 2023). "Three proteins, C1QTNF1, FGF-21 and CST3, reflecting dyslipidemia and kidney disease, displayed a higher association with HF in patients who did not undergo weight-loss-surgery and maintained with obesity." (PMID 35945262, 2022). "However, our study only found a relationship between BMI-defined obesity and cystatin C levels." (PMID 35185798, 2022). "We hypothesize that as Cystatin-C is related to hormonal influence, endotheliosis, and glomerular filtration rate, its higher expression was expected in OP due to the physiological mechanisms related to obesity and pregnancy." (PMID 36355174, 2022). "Besides, cathepsin S was discovered in obese subjects pointing out the potential shared pathophysiologic pathways between obesity and cardiovascular disease, and/or identifying altered glomerular permeability and consequently leading to serum cystatin C accumulation." (PMID 35862349, 2022). "Consistent with us, several observational studies demonstrated that cystatin C levels are correlated with the prevalence of T2DM and obesity in adolescents with age of 14-17 years independently of other confounding risk factors." (PMID 36482996, 2022). "Previously identified non-GFR-related factors such as inflammation, obesity, insulin resistance, oxidative damage, growth hormone, thyroid hormone and glucocorticoids have all instead been linked to increased cystatin C production and thus an underestimation of GFR." (PMID 34351595, 2022). "The study revealed significantly higher concentrations of uric acid, cystatin C, and mean GFR estimated by Filler formula in the obesity group than in the control group." (PMID 34442019, 2021). "In patients with clinically manifest vascular disease, EV-cystatin C levels were positively related, and EV-CD14 levels were negatively related to metabolic complications of obesity." (PMID 24498934, 2014).
Obesity (continued). "This study also suggests that obesity contributes to the development of CKD, which in turn contributes to the increase in serum cystatin C levels in obese patients." (PMID 24876964, 2014). "We used three anthropometric measures of obesity (BMI, WC, and WHR), and both creatinine and cystatin C as measures of kidney function." (PMID 25210651, 2013). "However, in recent years, it has become acknowledged that the cystatin C level may be affected by factors other than kidney function, including sex, race, obesity, greater height, current cigarette smoking, thyroid function, inflammation, glucocorticoid function, and malignancy." (PMID 21773013, 2011). "The most accurate predictor of the target AUC for all weight categories was cystatin C (MPE%: +0.2%, −2.0%, and −0.1% for patients with a normal weight, those who were overweight, and those who had obesity, respectively) with low imprecision (MAPE%: 9.8%, 9.5%, and 13.3%, respectively)." (PMID 40300860, 2025). "Physical activity, chronic diseases, and muscle mass are key determinants of creatinine levels, while obesity, smoking, and steroid use are considered major non-renal factors affecting cystatin C levels." (PMID 41333795, 2025). "Therefore, we suggest that future research implement other endogenous markers for kidney function, such as cystatin C and measured GFR in order to examine the role of GFR-estimating equations in children with overweight and obesity." (PMID 35211793, 2022). "We analyzed the differences in cystatin C levels between adolescents with obesity and adolescents without obesity of different sexes." (PMID 35185798, 2022). "In participants who mostly remained with obesity despite conventional (non-surgical) anti-obesity measures, C1QTNF1, FGF-21 and CST3 were associated with a significantly higher risk of HF compared with those who lost weight through surgical intervention." (PMID 35945262, 2022). "Population-based prospective studies should be carried out to overcome these limitations and comprehensively understand the cystatin C levels in adolescents with obesity and adolescents without obesity." (PMID 35185798, 2022). "Total cholesterol, serum creatinine, and CRP levels were comparable between lean and obese participants, whereas uric acid, cystatin-c, and PRA levels were elevated in obese patients, likely reflecting obesity-induced hyperfiltration and renal damage, respectively." (PMID 34095124, 2021). "After performing correlation analysis between cystatin C and ghrelin levels, a direct correlation was found (r = 0.67, t = 2.5, p <0.05) between the increase in both indicators in patients with stage 2 CKD on the background of obesity." (PMID 33456602, 2020). "Cystatin C and CD14 expression was reported to be pronounced in adipose tissue, suggesting a potential contribution of the adipose tissue-derived EVs to the advance of metabolic complications of obesity." (PMID 33339409, 2020). "The increase in cystatin C in the early stage of obesity without the decreased creatinine-based GFR is significant in terms of the ability of cystatin C to be used as an early marker in the evaluation of renal functions in obese children." (PMID 30035656, 2018). "In the present study, the obese subgroup presented mean BMI values that were representative of mild obesity and cystatin C levels were similar in obese and nonobese groups in both men (P = 0.104) and women (P = 0.484)." (PMID 24876964, 2014). "In the IVW approach, after adjusting for obesity, the casual relationship of OSA and eGFRcystatin c (OR = 0.995, 95% CI: 0.975–1.015, P = .626), BUN levels (OR = 1.039, 95% CI: 0.971–1.112, P = .269), and cystatin C levels (OR = 1.022, 95% CI: 0.919–1.136, P = .687) disappeared." (PMID 39928765, 2025). "The increase in mortality in women during the pandemic could be explained by the effects of obesity, angina and elevated Cystatin C levels (indicating kidney dysfunction), with those without higher education being more vulnerable." (PMID 39774287, 2025).
Obesity (continued). "Though the data are not definitive, cystatin C may be increased in smoking, obesity, chronic inflammation and use of medications such as thyroid hormones and glucocorticoids, leading to lower eGFRcys." (PMID 40973716, 2025). "However, obesity markers such as body fat, BMI, waist circumference or fat tissue index did not have a significant impact on the accuracy of cystatin C-based GFR estimation." (PMID 39792299, 2025). "In patients with inflammation (elevated CRP) or obesity, cystatin C levels may rise independent of filtration changes." (PMID 41516239, 2025). "The role of cystatin C in obesity is therefore not entirely clear." (PMID 39409098, 2024). "This has led some researchers to suggest that these limitations can in part be reduced using equations based on cystatin C levels, even if non-GFR-related factors, such as obesity, inflammation, and a history of smoking, can affect circulating cystatin c values." (PMID 38068404, 2023). "However, cystatin C synthesis is upregulated in adipose tissue in case of obesity and cystatin C does not improve reliability of GFR estimation over SCr in adults with overweight and obesity." (PMID 35211793, 2022). "Furthermore, in cystatin C-based formulae, a steady decline in GFR parallel to the duration of obesity may be noted, which may be an indication that functional damage was superceeded by structural damage over time." (PMID 30145854, 2019). "On the other hand, studies have shown that cystatin C levels may be dependent of adipose tissue, increasing directly as BMI increases, and, thus, it can underestimate GFR in individuals with higher levels of obesity." (PMID 24876964, 2014). "Cystatin C is an accurate biomarker for the early detection of AKI, and may, in selected populations, be superior to creatinine; however, data have been inconsistent and Cystatin C is modified by age, sex, muscle mass, obesity, smoking status, thyroid function, inflammation, and malignancy." (PMID 35207297, 2022). "In addition, cystatin C concentration is higher in patients with obesity, and these equations might not be accurate in obese individuals." (PMID 31228953, 2019). "All of these results with elevated inflammation markers (cystatin C, hs-CRP, NLR) in both NW and OW PCOS indicate that PCOS is formed depending on the inflammatory process and is independent of obesity." (PMID 35657129, 2022). "Simultaneously with the increase in the level of cystatin C and the decrease in the glomerular filtration rate, there was an increase in ghrelin levels in stage 2 CKD and the progression of obesity, while such dependence was not seen in stage 1 CKD." (PMID 33456602, 2020). "Whether obesity is associated with hyperfiltration in the non-diabetic general population, remains unresolved due to a lack of consensus regarding the definition of hyperfiltration and the limited precision of high-range GFR estimations with creatinine and/or cystatin C." (PMID 27832768, 2016). "Obesity alters the pharmacokinetics of vancomycin and affects cystatin C levels independent of GFR, and thus the performance of cystatin C-based dosing models in this population needs further study." (PMID 24887089, 2014). "Prior studies have suggested that obesity may increase cystatin C levels independent of kidney function, which leads to an underestimation of GFR using the cystatin C equation." (PMID 38646842, 2024). "In this way, cystatin C, hs-CRP, and NLR, which we can call inflammation markers, are higher in adolescents with both NW and OW PCOS than controls, supporting that PCOS develops in the inflammatory process, independent of obesity." (PMID 35657129, 2022). "In contrast to other studies performed in patients without known cardiovascular disease, we could not demonstrate a relation between obesity and circulating EV-cystatin C-levels, nor were HOMA-IR levels significantly related to EV-cystatin C levels." (PMID 24498934, 2014).
kidney damage (84 papers, 2012 to 2026). "In patients with uric acid stones, elevated serum creatinine and cystatin C levels are often associated with kidney damage." (PMID 40551898, 2025). "The diagnostic role of cystatin C as an indicator of kidney damage has been broadly studied in humans." (PMID 38132490, 2023). "In terms of gene expression markers indicative of kidney damage, we analyzed Cystatin C, KIM-1, and neutrophil gelatinase-associated lipocalin (NGAL) in both kidneys." (PMID 37999512, 2023). "Specifically, we aimed to assess the diagnostic accuracy of cystatin C for diagnosing DN by comparing it with the traditional markers of nephropathy such as albuminuria, serum creatinine, and serum creatinine-based eGFR in the Nepalese population." (PMID 33996155, 2021). "Future inclusion of Cystatin C may prove beneficial in elucidating patients at increased risk of kidney damage." (PMID 38932813, 2024). "Albuminuria and/or proteinuria, serum creatinine, glomerular filtration rate, and cystatin C, together with urinary microscopy and renal biopsy are often assessed for diagnostic, evaluation of kidney damage, monitoring of disease progression, and monitoring of treatment." (PMID 35722479, 2022). "The urine concentrations (relative to creatinine) of markers of kidney damage, that is, cystatin C and TIM-1, were similar between the groups." (PMID 41102944, 2025). "The nephropathy group exhibited the highest mean levels of cystatin C and lowest eGFR of all groups." (PMID 41009467, 2025). "Our study further explored the potential biomarkers of kidney damage in plasma and showed significant differences in the levels of cystatin C, TFF3, and uromodulin between patients with progressive nephropathy and their control subjects." (PMID 39937009, 2025). "Co-treatment with BBR (50 mg/kg) significantly reduced CPS-induced kidney damage, as demonstrated by lower serum urea, creatinine, uric acid, cystatin C and NGAL levels by 33 %, 48 %, 44 %, 55 % and 56 % respectively, compared to the CPS-alone group." (PMID 38327393, 2024). "The Xiang study showed that patients with severe COVID-19 had a high level of biochemical indicators of renal function like BUN, cystatin C, and creatinine, indicating kidney damage." (PMID 37217858, 2023). "In this study we found that the cystatin C level of the type 2 DM is increased significantly and associated with lipoproteins in T2DM patients diagnosed nephropathy." (PMID 37082121, 2023). "A statistically significant increase in NT-proBNP (p < 0.001) and cystatin C (p < 0.001) values was found between healthy subjects and subjects with heart and kidney damage (Mann–Whitney U test)." (PMID 36553138, 2022). "We restricted our analyses to predictive modeling with known or possible risk factors, including demographic indicators, biomarkers of kidney function and kidney damage, such as ethnicity, serum cystatin C and renalase." (PMID 36339144, 2022). "The closest to the recommended CKD-EPI formula was GFR, calculated taking into account the rate of cystatin C as an early marker of kidney damage." (PMID 35928354, 2022). "Serum creatinine recognized 12% and serum cystatin C identified 40% of type 2 diabetic patients with nephropathy, while in another study, serum cystatin C discriminated between normoalbuminuria and microalbuminuria in type 2 diabetic patients." (PMID 33401560, 2021). "A significant difference in HDL cholesterol (p=0.018) and serum cystatin C (p < 0.001) was observed among different grades of nephropathy." (PMID 33996155, 2021). "Cystatin C is an important cysteine protease inhibitor in the human body and is proposed as a new indicator of glomerular filtration rate for the detection of kidney damage." (PMID 33134263, 2020). "postoperative hour cystatin C, interleukin-18 (IL-18), and neutrophil gelatinase-associated lipocalin (NGAL) parameters were measured for early detection of kidney damage." (PMID 33118738, 2020).